STAT1 (signal transducer and activator of transcription 1)
Diseases named in the same sentence as STAT1 in open-access papers (continued):
Sharing a sentence is not in itself a finding about the gene and the disease.
melanoma (continued). "NOS1 reduces the recruitment of STAT1-mediated HDAC2 to ISG promoters and promotes lung metastasis of melanoma through the S-nitrosylation of HDAC4-C16/C229." (PMID 38877096, 2024). "Recently, it has been shown that IFN‐γ induces STAT1‐dependent upregulation of miR‐29, which reduces CDK6 expression and induces G1‐arrest in melanoma cells." (PMID 39575303, 2024). "In colorectal cancer and melanoma, defects in METTL3 or METTL14 promote IFN-γ-Stat1-Irf1 signaling by stabilizing STAT1 and IRF1 mRNA expression in an m6A-YTHDF2-dependent manner, thus upregulating PD-L1 expression and making tumors more sensitive to PD-L1." (PMID 38762484, 2024). "IL6RIL6 has shown favorable clinical efficacy as a whole‐cell melanoma vaccine, but it directly activates STAT3 phosphorylation, potentially inhibiting the IFN‐γ‐STAT1 pathway." (PMID 38973154, 2024). "In melanoma cell lines A375, A2058, and RPMI-7951, apigenin resulted in decreased G1 and S phase cell counts alongside decreased levels of IFN-γ and STAT1 phosphorylation while enhancing T cell activity and upregulating IL-2 levels." (PMID 39690423, 2024). "PRELPhigh melanoma cells express increased levels of NLRC5 as well as selected IFN-γ signal transduction molecules, e.g., IRF1, IRF5, STAT1 and STAT2." (PMID 37730606, 2023). "Apigenin, in the case of melanoma (melanoma xenograft model with A375, A2058, and RPMI-7951), strongly suppresses the IFN-γ-induced activation of STAT1, leading to decreased PD-L1 expression; thus, sensitizing them to T cell-mediated killings." (PMID 38139779, 2023). "NOS1 was identified as an inhibitory factor released by melanoma cells, which led to dysfunctional IFN-α p-STAT1 signaling in PBMCs." (PMID 37741983, 2023). "We further found that TET2/3, STAT1/3 and CD274 were more highly expressed in anti-PD1-treated Yumm1.7-derived melanoma cells than in similarly treated B16F10 cells." (PMID 36854755, 2023). "In a later study, 14 melanoma patients were treated with high-dose IFN and assessed for signaling responsiveness through phosphoflow cytometry of IFN-α-induced p-STAT1 in peripheral blood lymphocytes." (PMID 37741983, 2023). "Apigenin, along with a significant pro-apoptotic capacity in melanoma cells, has been shown to exhibit inhibitory effects on IFN-γ-induced expression of PD-L1 through inhibition of STAT1 phosphorylation." (PMID 36768978, 2023). "In order to further investigate the relationship between gene expression levels of STAT1, IRF1, and FLI1 and survival probability in melanoma patients, Kaplan-Meier survival plots of high and low gene groups for these TFs were utilized." (PMID 37435067, 2023). "The 12 TFs that were inferred to regulate NK and T cells activation in these modules are shown as follows: Module M1 contained the regulators IRF1, STAT1, SPI1, FLI1, IRF7, and E2F1, which are essential regulators for C4 Melanoma CORO1A." (PMID 37435067, 2023). "Together, our work describes how IFN/STAT1 can induce NAMPT in human and mouse melanoma cells to increase growth both in vitro and in vivo." (PMID 36900204, 2023). "Using immunoprecipitation, we detected an interaction between STAT1 and PARP14 in three melanoma cell lines—MV3, LOX-IMVI, and YUMM2.1." (PMID 37752135, 2023). "The STAT1 and STAT2 pathways in melanoma cells are sensitized to IFN-α by pretreatment of the cells with IFN-γ." (PMID 37047709, 2023). "Collectively, these results indicate that crosstalk with Activin-A signaling can augment STAT1 activation by IFN-γ and confer resistance to anti-proliferative IFN-γ/JAK signaling within melanoma cells." (PMID 38304252, 2023). "Whereas STAT1 abrogates growth and mediates anti-tumor effects, STAT3 promotes cell proliferation and tumorigenicity as it has been shown in melanoma and head neck squamous cell carcinoma." (PMID 37047709, 2023). "A total of 12 TFs were identified, among which the expression of STAT1, IRF1, and FLI1 in C4 Melanoma CORO1A was higher than that of other subtypes." (PMID 37435067, 2023).
melanoma (continued). "As was observed for melanoma cells, IFNγ treatment of Ptpn2 knockout CT26 and MC38 cells enhanced the expression of the IFNγ response genes Cxcl1, Ccl5, Stat1, Stat2, Stat3, Irf1, Pd-l1, Tap1, and Casp8, compared with IFNγ-treated control cells." (PMID 36968224, 2023). "A six-gene IFN-γ signature (including IDO1, CXCL10, CXCL9, HLA-DRA, STAT1, and IFNG) was identified in a melanoma cohort of the KEYNOTE-001 study to predict response to pembrolizumab." (PMID 35222540, 2022). "STAT1 has also been found through a two-cell CRISPR-type screen including human T cells as effectors and melanoma cells as targets to be upregulated, affecting immunotherapy response." (PMID 36135194, 2022). "Our study demonstrated that both the expression levels and activation of STAT1 and STAT3 in melanoma were increased after IFN-γ treatment, which were abolished by co-treatment with nNOS inhibitors." (PMID 35105915, 2022). "The mechanism of immune therapeutic response dependent on USP22 involves STAT1 stabilization via deubiquitination and promotes the FN-JAK1-STAT1 signal, which is a pathway involved in immune therapy resistance in melanoma." (PMID 35884430, 2022). "MMP2 is secreted from melanoma cells and then cleaves IFNAR1, leading to inactivation of DCs, induction of T helper 2 (Th2) cell polarization and low levels of STAT1 phosphorylation." (PMID 36104718, 2022). "We confirmed that this effect was driven by inhibiting STAT1 gene expression and STAT1 phosphorylation, thereby downregulating the PD-L1/PD-L2 transcriptional regulator IRF1 in both human and mouse melanoma cells." (PMID 34832863, 2021). "As for anti-PD-1 blockade, the IFN-γ gene signature (IDO1, CXCL10, CXCL9, HLA-DRA, STAT1, and IFNG) predicts the response to anti-PD-1 therapy in multiple tumors, including melanoma." (PMID 34439264, 2021). "Recently, a study of LNK expression in melanoma found that in melanoma cells, interferon (IFN)-STAT1 signalling induced LNK expression." (PMID 35056081, 2021). "EGCG downregulated the basal expression of STAT1 mRNA, but IFN-γ upregulated its expression (3–11-fold) in all three human melanoma cell lines." (PMID 34832863, 2021). "In agreement with mRNA changes, the IFN-γ treatment increased p-STAT1/STAT1 and IRF1 protein levels, which were abolished by adding EGCG in all three melanoma cells." (PMID 34832863, 2021). "In the KEYNOTE-001 study, six gene signatures of INFG-related genes (IDO1, HLA-DRA, STAT1, CXCL9, IFNG and CXCL10) were previously developed in melanoma patients." (PMID 32107458, 2020). "Our results showed that RELA and STAT1 activated NVD-BM expression in the presence of doxycycline, and slowed melanoma cell growth and migration." (PMID 32712598, 2020). "The dual-input signals, RELA proto-oncogene (RELA) and signal transducer and activator of transcription 1 (STAT1), activated NVD-BM expression and repressed melanoma cell proliferation and migration." (PMID 32712598, 2020). "In this study, we demonstrate that in melanoma cells, BRAF inhibition curtails IFN‐γ‐induced PD‐L1 expression through two complementary mechanisms: decreased STAT1 activity and attenuation of protein translation." (PMID 32330348, 2020). "STAT1 and IL-32 signaling mediates immunoresponse upon TLR2/6 agonists and IFN-gamma treatment in melanoma." (PMID 31024232, 2019). "High level of IFN-β activates STAT1, STAT2 and STAT3 to facilitate cellular dormancy in tumor-repopulating melanoma cells." (PMID 30546090, 2019). "Inhibition of STAT1 phosphorylation by STATTIC has also been described in human ovarian cancer cells and melanoma cells." (PMID 30283459, 2018). "Melanoma regression after therapeutic ICB with pembrolizumab requires pre-existing CD8+ T cells and phosphorylated STAT1 expression at the invasive margin." (PMID 30477280, 2018). "It has been reported that STAT1 protein can be up-regulated by IFN-alpha, gamma and lambdas in human hepatoma cells, melanoma cell lines and Raji cells, respectively." (PMID 28623917, 2017).
melanoma (continued). "In the current study, we demonstrate that nitration can occur at position 701 of the STAT1 protein in PBMC derived from both pancreatic cancer and melanoma patients." (PMID 29133913, 2017). "These pathways including ERK1/2, STAT1, STAT3, STAT5, AKT and mTOR are known to drive the tumoral progression in melanoma cells and are found to be crucial in the interactions of melanoma with its microenvironment and progression to metastasis." (PMID 28223541, 2017). "The melanoma cell line ESTDAB-004 expresses STAT1, but the STAT1 expressed lacks phosphorylation at Y701." (PMID 25690042, 2015). "B16F1 mouse melanoma cells harboring the HyBNAR construct specifically bound Hu-IFN-Is and were rendered sensitive to Hu-IFN-I stimulated anti-proliferation, STAT1 activation and activation of a prototypical IFN-I response gene (MX2)." (PMID 24416207, 2014). "In three different human melanoma cell lines, SK-MEL-13, -28, and -37, IL-27 induced tyrosine phosphorylation of STAT1 and STAT3, indicating that these cells were responsive to IL-27." (PMID 24155891, 2013). "Altogether, these data substantiate for the first time a time-dependent up-regulation of the expression of pri-29a~b-1 cluster as well as of the mature miRNAs miR-29a and -29b in melanoma cells, which is triggered by IFN-γ-induced STAT1 signaling." (PMID 23245396, 2012). "Deregulated JAK3 and RNase L pathways in LNCaP prostate cancer cells, defective STAT1 and STAT2 activation in fibrosarcoma and melanoma cells and down-regulated IFNAR in high grade bladder cancer have all been reported to disable the innate immune signaling." (PMID 22194884, 2011). "To investigate the potential antitumoral role of IFN-λ, we first evaluated the response of B16 melanoma cells to IFN-λ, by analyzing STAT1 activation and MHC class I antigen expression." (PMID 22190970, 2011). "Despite a similar degree of cytotoxicity and the ability to reduce basal pSTAT3 in human melanoma cells, the WP1066, JSI-124, and Stattic compounds also inhibited IFN-γ-induced STAT1 phosphorylation." (PMID 20576164, 2010). "IFNγ/STAT1 signaling is known to be both a crucial player in anti-tumoral immune responses as well as a strong activator of immunosuppressive IDO1 expression, particularly in melanoma." (PMID 39962447, 2025). "This bidirectional regulatory pattern was particularly evident in STAT1 and IRF3 downstream signatures, further supporting the hypothesis that CCRL2 serves as a key modulator of innate immune gene programs in melanoma cells." (PMID 40867595, 2025). "Notably, STAT3 and STAT1 were among the top-ranked targets, further supporting the potential involvement of the JAK-STAT signaling pathway in MBP’s anti-melanoma activity." (PMID 40508400, 2025). "In addition, they found that Tan IIA stimulated the downregulation of signal transduction and transcription factor STAT1, leading to the downregulation of PTGS2 and inhibiting ferroptosis in melanoma." (PMID 40932870, 2025). "IFNs can improve ICI responses as loss-of-function mutations in IFN signaling components (i.e., JAK1/2) have been identified in melanoma patients after pembrolizumab treatment relapse, and knockout of IFN pathway mediators such as Jak1, Stat1, Ifngr1 in tumors can weaken ICI treatment efficacy." (PMID 39663510, 2025). "Interferons mediate distinct responses: IFN-γ promotes the maturation of cDC2 cells, enhancing NK cytotoxicity in leptomeningeal metastases, while melanoma resistance to IFN-α involves STAT5 overexpression, counteracting STAT1-mediated antiproliferative signaling." (PMID 41465101, 2025). "Experiments on melanoma cell lines have also indicated significant upregulation of PD-L1 expression with the activation of several transcriptional genes, specifically JAK2, STAT1, STAT2, STAT3, IRF1 (interferon regulatory factor 1), and IRF9, in response to IFN-γ stimulation." (PMID 39690423, 2024).
melanoma (continued). "Indeed, in melanoma cells, the RG4 within the 5′UTR of STAT1 mRNA inhibits the translation of this factor, known to induce PD-L1 transcription." (PMID 38828391, 2024). "The activation of the STING pathway by VPS34 inhibition was not limited to the RCC cells but similarly observed in the Me30966 melanoma cell line as evidenced by increased IRF3 and STAT1 phosphorylation (lanes 3 and 5) in a STING‐dependent manner (lanes 4 and 6)." (PMID 38506049, 2024). "For instance, in a murine model of transplanted melanoma, prophylactic application of TLR4/9 agonists (before tumor inoculation) can activate the IFNγ/STAT1 signaling pathway, promoting tumor cell autophagy and autophagy-related tumor cell death, subsequently reducing metastasis." (PMID 38523155, 2024). "In addition, the mRNA abundance of PARP14 in both melanoma cells and patient samples (TCGA SKCM) positively correlated with that of STAT1, IFNG, and CD274." (PMID 37752135, 2023). "In detail, quercetin inhibited melanoma cell proliferation and invasion through RIG-I (retinoic acid-inducible gene I)-induced upregulation of IFN-α and IFN-β expression, resulting in activation of the STAT1 signaling." (PMID 36768978, 2023). "Unlike in melanoma, our results highlight the important role of Jak2 and Stat1 in inducing PD‐L1 expression in HNSCC." (PMID 36515567, 2023). "For example, miR-146a was upregulated in melanoma micro-environmental tissue and miR-146a could inhibit the level of IFN-γ by repressing the expression of STAT1, thus suppressing the abilities of melanoma proliferation and migration." (PMID 36600320, 2023). "In order to study the effect of the selective regulation of the two STAT1 protein isoforms on PD-L1 expression, we depleted each of them separately by using specific siRNAs in the BRAF V600E mutant A375 melanoma cell line." (PMID 35267483, 2022). "Not much information is available concerning MX1 and MX2 during SARS-CoV-2 infection; however, in melanoma cell lines, it was reported that persistent IFN-γ stimulation increases the expression and genome occupancy of STAT1 and induces the expression of ISGs, such as IFIT1 and MX1." (PMID 36298734, 2022). "Treg signature genes CXCR5, TNFRSF9, CCR7, STAT1, GBP4, and EOMES were significantly upregulated in the young cohort and were correlated with higher survival in melanoma, while ID3, IL-17A, IL-17F, RDH10 and IL-11 were significantly upregulated in the old cohort." (PMID 36135194, 2022). "Given the close interaction between STAT1 and MYO1F (Pearson ρ = 0.32, p = 9.88E − 4), these observations also support the regulatory roles of MYO1F in M1-polarization and STAT1 activation in macrophages, leading to increased IFN-γ secretion in the melanoma microenvironment." (PMID 33619278, 2021). "Therefore, we suggest that DHA suppressed melanoma invasiveness by reducing MMPs and EMT activity and expression through inhibiting the constitutive activities STAT3/NF-κB and accelerating the STAT1." (PMID 34539408, 2021). "Thus, our genetic circuit effectively sensed the dual-input of RELA and STAT1 signals, and induced NVD-BM actuator expression to rebuild cholesterol metabolism by converting cholesterol to 7-DHC, promoting melanoma cell regression." (PMID 32712598, 2020). "Moreover, IFNγ signatures (CXCL10, CXCL9, IDO1, IFNG, and STAT1) and myeloid lineage phenotypic and functional markers (CD14, CD163, CD33, and CD68) were also significantly increased in melanoma patients with high ETV7." (PMID 33424867, 2020). "Others have reported that the transcription factors JAK/STAT1, IRF-1 and NF-kB, involved in inflammatory cytokine production, can contribute to IFN-g-induced PD-L1 expression on hematopoietic tumors, lung cancer, and melanoma, respectively." (PMID 31730010, 2019).
melanoma (continued). "Melanoma cells exposed to recombinant IFN protein [either type I (alpha, beta) or type II (gamma)] quickly activated the interferon signaling pathway, as evidenced by heavy phosphorylation of STAT1 as early as 30 min following IFN treatment." (PMID 31110180, 2019). "The overactivation of STAT5 has been shown to inhibit STAT1-mediated IFN-α responses and induction of IRGs in melanoma cells by increasing the expression of cytokine-inducible SH2 protein (CIS), which promotes ISRE suppression by blocking binding of STATs to JAK-associated IFNAR." (PMID 31842362, 2019). "In both melanoma and lung cancer models, impaired STAT1 phosphorylation in response to IFN-γ resulted in low MHC inducibility and reduced IFN-γ sensitivity due to defective JAK signal transduction has been reported in human melanoma and lung carcinoma models." (PMID 31842362, 2019). "For example, in melanoma cells, miR-29a could be up-regulated by IFN-γ in STAT1-dependent signaling." (PMID 31217935, 2019). "It has been further suggested that a balance between STAT1, STAT3, and STAT5 expression, upon interferon-mediated activation, impact the heterodimerization and transcriptional mechanisms driven by JAK-STAT activation in melanoma." (PMID 30166456, 2018). "We additionally found other routes of GH induced signaling downstream of JAK2 and SRC, including GH-induced increases in phosphorylation states of STAT5, STAT1, STAT3 as well as of AKT, mTOR, and ERK1/2 in all four human melanoma cell lines." (PMID 28223541, 2017). "Therefore, a novel liquid chromatography-tandem mass spectrometry assay demonstrated that nitration of the STAT1-Tyr701 occurs in PBMC derived from both pancreatic cancer and melanoma patients." (PMID 29133913, 2017). "Our data indicated that dysregulated IFN-γ secretion by NK cells contributed to a significant defect in STAT1 but not STAT5 activation in patients with advanced melanoma in response to IL-2 stimulation." (PMID 27153543, 2016). "Other recent studies have examined the response of T and NK lymphocytes from melanoma patients to type I and type II interferons (IFN), where a defective activation of STAT1 in response to IFN-α and IFN-γ was found in some lymphocyte subsets relative to healthy controls." (PMID 27153543, 2016). "Furthermore, our data revealed that IFNα clearly activates phosphorylation of STAT1 and STAT3 in THP1 and A375 melanoma cells." (PMID 26735690, 2016). "For example, in B16 melanoma cells, although IFN-λ induced a very weak STAT1 activation in comparison with IFN-α, we observed a robust stimulation of MHC class I expression at the cell surface, indicating the potential contribution of cell-specific modulators of the IFN-λ activity." (PMID 22190970, 2011). "Notably, in melanoma cells with NOS1 overexpression, the level of IRF7 induced by IFNα is similar to that observed in control cells, which suggests that the JAK/STAT1 pathway remains unaffected by NOS1." (PMID 41535256, 2026). "Finally, we analyzed scRNA-seq data from two melanoma patients and specifically investigated whether combined HH/GLI and IFNγ/STAT1 signaling would affect the relative amount of IDO1 positive tumor cells." (PMID 39962447, 2025). "IFN‐γ‐STAT1 is an important pathway for anti‐tumor immunity after immune infiltration, and the inhibition of its pathway may limit the potential of IL6RIL6 as an mRNA vaccine intratumoral injection for melanoma treatment." (PMID 38973154, 2024). "For the treatment of melanoma, hydroartemisinin could significantly reduce the levels of p-STAT3, p65, and IL-10 induced the p-STAT1 both in vitro and in vivo, indicating that dihydroartemisinin exhibits anticancer effects on melanoma by affecting STAT1/STAT3 pathway." (PMID 39202965, 2024).